KLC3 (kinesin light chain 3)
Description:
Kinesin is a microtubule-associated force-producing protein that may play a role in organelle transport. Plays a role during spermiogenesis in the development of the sperm tail midpiece and in the normal function of spermatozoa (By similarity). May play a role in the formation of the mitochondrial sheath formation in the developing spermatid midpiece (By similarity).
Synonyms: KLC2; KLC2L; KNS2B; KLCt
Tractability: PROTAC: ubiquitination databases record sites on it.
Gene: Protein-coding gene on chromosome 19 (45,333,434 to 45,351,537, forward strand). Ensembl gene ENSG00000104892.
Subcellular location: Cytoplasm, cytoskeleton; Mitochondrion
Subcellular location (Human Protein Atlas): Centriolar satellite; Cytosol; Nucleoplasm
Pathways (Reactome):
Hemostasis: Kinesins
Immune System: MHC class II antigen presentation
Signal Transduction: RHO GTPases activate KTN1
Vesicle-mediated transport: COPI-dependent Golgi-to-ER retrograde traffic
Gene Ontology:
Molecular function: protein binding; kinesin binding
Biological process: microtubule-based movement; sperm mitochondrial sheath assembly; spermatid development; spermatogenesis
Cellular component: cytoplasm; mitochondrion; cytoskeleton; kinesin complex
Genetic constraint (gnomAD): Loss-of-function variants: 73 observed, 54.84 expected, observed/expected ratio (o/e) 1.33, 90% interval 1.1 to 1.62. The synonymous counts are far from expectation, so gnomAD's model fits this gene poorly and the ratio says little. Missense variants: 848 observed, 625.79 expected, observed/expected ratio (o/e) 1.36, 90% interval 1.28 to 1.43. Synonymous variants: 377 observed, 257.02 expected, observed/expected ratio (o/e) 1.47, 90% interval 1.35 to 1.6.
Homologues: Orthologues: chimpanzee KLC3 (99% identical), macaque KLC3 (97% identical), pig KLC3 (92% identical), dog KLC3 (92% identical), mouse Klc3 (91% identical), guinea pig KLC3 (88% identical), rat Klc3 (82% identical), zebrafish klc3 (61% identical), tropical clawed frog klc4 (57% identical), zebrafish klc4 (18% identical). Paralogues in human: KLC4 (63% identical), KLC1 (60% identical), KLC2 (60% identical), NPHP3 (31% identical), APPBP2 (21% identical).
Diseases named in the same sentence as KLC3 in open-access papers:
KLC3 is named in the same sentence as 13 diseases in open-access papers, as found by Europe PMC text mining. Sharing a sentence is not in itself a finding about the gene and the disease. The quoted sentences say what the papers report.
infertile (2 papers, 2016 to 2024). "It was interesting that it was observed a positive significant correlation between abnormal sperm midpiece and the relative expression of KLC3 in infertile individuals." (PMID 27141544, 2016). "So, the infertile individuals were classified into three groups based on this criterion; individuals with normal level of KLC3 expression, higher or lower than normal range of expression." (PMID 27141544, 2016). "This study for the first time aims to compare the expression of the KLC3 gene between fertile and infertile individuals." (PMID 27141544, 2016). "Our results revealed a significant correlations between sperm concentration with relative expression of KLC3 only in infertile groups (r=0.45, p=0.00)." (PMID 27141544, 2016). "Following the assessment of relative KLC3 expression in 19 fertile and 57 infertile individuals, the distribution of KLC3 in fertile individuals were defined lower and upper 10 percentiles." (PMID 27141544, 2016). "Out of 57 infertile individuals, 4 and 17 showed lower and higher level of KLC3 expression, respectively, and 36 individuals were within the normal range." (PMID 27141544, 2016). "Considering the role of KLC3 in formation of mitochondrial sheaths, which has important function in motility, infertile individuals were categorized into asthenozoospermic and non-asthenozoospermic individuals." (PMID 27141544, 2016). "Kinesin light chain 3 (KLC3), for instance, connects mitochondria, and its failure to bind outer dense fibers results in abnormalities in the mitochondrial sheath, changing progressive motility and causing infertility." (PMID 39020374, 2024). "Then, it was categorized infertile individuals based on the normal range of expression of KLC3." (PMID 27141544, 2016). "Therefore, the relative expression of KLC3 was evaluated in fertile and infertile individuals." (PMID 27141544, 2016).
asthenozoospermia (1 paper, 2016). "In conclusion, the results of this study state that aberrant expression of KLC3 might be associated with phenomena like oligozoospermia and asthenozoospermia." (PMID 27141544, 2016). "The results of this study show that aberrant expression of KLC3 might be associated with phenomena like oligozoospermia and asthenozoospermia." (PMID 27141544, 2016).
Hypertension (1 paper, 2025). The presence of chronic increased pressure in the systemic arterial system. "Although there is currently no research reporting the association of the genes P2RY10, GPR171, KLC3, and LYSMD3 with hypertension, these genes may indirectly affect the occurrence of hypertension." (PMID 39854379, 2025).
lung carcinoma (1 paper, 2022). "Moreover, it was reported that the wild type alleles of kinesin light chain 3 (KLC3) Lys751Gln were significantly correlated with greater smoking intensity, and genetic variations may influence the progression of lung cancer." (PMID 35097114, 2022).
nicotine addiction (1 paper, 2015). "Attending our results, across SNPs, XRCC3 Thr241Met and KLC3 Lys751Gln polymorphisms could be related to nicotine addiction measured as smoking amount (PYS) or years smoking." (PMID 26017978, 2015). "In addition, smokers with the XRCC3 Thr241or KLC3 Lys751 alleles presented more nicotine addiction measured by FTND and more years smoking." (PMID 26017978, 2015).
osteoarthritis (1 paper, 2024). A noninflammatory degenerative joint disease occurring chiefly in older persons, characterized by degeneration of the articular cartilage, hypertrophy of bone at the margins and changes in the synovial membrane. "We recognized 22 of these genes as druggable according to the DGIdb database, such as MTF1, KLC3, STAT3, LIFR, and CBFB, making them potential targets for osteoarthritis therapy." (PMID 39796139, 2024).
cancer (2 papers, 2017 to 2021). A tumor composed of atypical neoplastic, often pleomorphic cells that invade other tissues. "However, to our knowledge, the role of KLC3 in cancer has not been studied." (PMID 34346563, 2021).
KLC3 also shares sentences with these, for which no sentence is quoted: tumor (2 papers); breast carcinoma (1); cardiomyopathy (1); left ventricular hypertrophy (1); macrosomia (1); pancreatic cancers (1).